CD82 (CD82 molecule)
Diseases named in the same sentence as CD82 in open-access papers (continued):
Sharing a sentence is not in itself a finding about the gene and the disease.
melanoma (26 papers, 2011 to 2023). A malignant, usually aggressive tumor composed of atypical, neoplastic melanocytes. "Studies found that downregulation of KAI1/CD82 mRNA expression in human melanoma cell lines was related to loss of heterozygosity or allelic imbalance." (PMID 34306081, 2021). "Previously, we have identified a novel human metastasis-inducing lncRNA (named SKAI1BC), that suppresses the KAI1/CD82 metastasis-suppressing gene and is upregulated in triple negative breast cancer and melanoma derived cell lines." (PMID 37990044, 2023). "For instance, miR-338-5p promotes the proliferation and metastasis of melanoma cells by targeting CD82 molecule." (PMID 35030979, 2022). "KAI1/CD82 expression also inhibited melanoma cell-induced gap formation, melanoma cell extravasation in vitro, and subsequent lung metastasis development in vivo." (PMID 34306081, 2021). "With regard to other cancer types, miRNAs have also been observed to promote cancer metastasis via their modulation of CD82 expression in hepatocellular cancer, malignant melanoma and gastric cancer." (PMID 34503296, 2021). "Decreased CD82 expression was reported to be significantly correlated with advanced disease and poor prognosis in melanomas." (PMID 34503296, 2021). "KAI1/CD82 can suppress the ability of melanoma cell invasion and migration by reducing the activity of metalloproteinase-2 or by using another tumor suppressor protein called inhibitor of growth 4, which regulates p65." (PMID 34306081, 2021). "In highly metastatic melanoma cells, the expression of KAI1/CD82 increased p21 expression upon binding of the Duffy antigen receptor group (DARC)." (PMID 34306081, 2021). "MiR-338-5p induced melanoma cells proliferation and metastasis via CD82 targeting and p-AKT upregulation." (PMID 33827418, 2021). "For example, reports suggest that CD82 expression in melanoma cells inhibits tumour cell extravasation and lung metastasis formation in vivo; upregulation of CD82 predicted better outcome in our analysis of two independent cohorts." (PMID 29193607, 2018). "Tspan8 was originally identified as a tumor-associated antigen by an antibody (CO-029), CD63 by a melanoma-associated antigen (ME491), CD151 was re-identified by an antimetastatic antibody, and CD82/KAI1 as a metastasis suppressor gene." (PMID 29946318, 2018). "KAI1/CD82, a member of Transmem-brane superfamily 4 (Tetraspanin), has beenassociated with the formation of hepatic metastasis of malignant melanoma." (PMID 29201802, 2017). "In melanoma the most important genes include GAS1, BRMS1, nm23, KISS1, KAI1 (CD82), SSeCKS, SMAD7, and Gelsolin." (PMID 33870460, 2021). "Several other tetraspanins, mainly CD9, CD81, CD82 and CD151 have been described to regulate proMMP-2 and/or proMMP-9 expression in cancer cell lines from liver, kidney, breast and lung carcinomas, fibrosarcomas and melanomas." (PMID 32455575, 2020).
lung carcinoma (18 papers, 2003 to 2024). "CD82 was reported to suppress lung cancer metastasis and its high expression was associated with poor LUAD prognosis." (PMID 37488117, 2023). "CD82 is a tetraspanin that, when expressed at low levels and in the context of elevated Vimentin expression, was associated with a worse lung cancer patient prognosis." (PMID 35280793, 2022). "For example, N-glycosylation at the Asn157 of CD82 decreased metastases in lung cancer and adhesion in colorectal cancer via down-regulating Wnt/β-catenin activation." (PMID 38765115, 2024). "Recently, a peptide mimicking the small extracellular domain (EC1) of CD82 has been used to treat various cancer cells, including colon, breast, prostate, and lung cancer cells." (PMID 34503296, 2021). "Anti-inflammatory responses leading to the downregulation of cytokine signalling also induce the expression of CD82 in a human lung carcinoma cell line." (PMID 34503110, 2021). "Jee and colleagues demonstrated that KAI1/CD82 upregulated TIMP-1 to suppress tumor cell invasion in lung carcinoma model." (PMID 23840773, 2013). "On the contrary, it has been reported that in lung cancer PC-14 cells, NF-kappaB inhibition suppresses expression of KAI1/CD82, a known metastasis suppressor for several human cancer types." (PMID 24213137, 2011). "It was found that expression of CD82/KAI1 was decreased with the progression of human lung cancer." (PMID 34503110, 2021). "There are several pathways by which KAI1/CD82 could suppress lung cancer metastasis." (PMID 34306081, 2021). "CD82, also known as KAI1, is an established metastasis suppressor in various malignancies, including lung cancer." (PMID 37488117, 2023). "In the previous study, the downregulated genes CASP10 and CD177 and the upregulated genes BAK1, ST14, CD82, and MUC4 were detected as biomarkers for lung cancer by the joint sparse regression model." (PMID 35923697, 2022). "In this same study, the EC1 amino acid sequence mimic peptide of CD82 (CD82EC1-mP) was successful in inhibiting cell migration, invasion and adhesion in vitro, while also suppressing metastasis in lung cancer cells in mice." (PMID 34503296, 2021). "By applying targeted mass spectrometry with stable isotope-labeled peptide standards, we assessed the levels of 28 EV-associated proteins, including the conventional exosome markers CD9, CD63, CD81, CD82, and HSPA8, in vesicles derived from the lung cancer cell lines NCI-H23 and A549." (PMID 34684727, 2021). "However, as the human ROS1 gene promoter lacks κB elements and not all human lung cancer cell lines express ROS1 protein, including A549 and H1299 which are fusion-negative cell lines, we further investigated the role of CD82 in epithelial lung cancer cell growth." (PMID 34503110, 2021).
pancreatic cancer (17 papers, 2002 to 2024). "Prkd1-deficiency in pancreatic cancer cells increases α6β4 loading into extracellular vesicles that requires CD82." (PMID 35159011, 2022). "KAI1/CD82 expression is downregulated in malignant tumors and is closely associated with malignant progression and metastatic spread and prognosis (including breast, colon, lung, ovarian, nasopharyngeal, liver, and pancreatic cancers)." (PMID 39769169, 2024). "Zhang and co-workers demonstrated that CD82 mediated the suppressive effect of TIMP-1 on the migratory activity of the pancreatic cancer PANC-1 cells." (PMID 36291767, 2022). "This attenuation of EGFR signalling by CD82 explains for its recently identified role as metastasis suppressor gene for prostate and pancreatic cancer." (PMID 11953881, 2002). "A reduced expression of CD82 has been reported in pancreatic cancer metastases." (PMID 34503296, 2021). "A recent study showed that CD82 inhibits the EMT process in pancreatic cancer by increasing E-cadherin expression and reducing the expression of Snail, vimentin, MMP2, and MMP9, which are involved in different steps of the EMT process, thereby effectively reversing the EMT process." (PMID 34503296, 2021). "Another study suggests combined detection of exosomal GPC1, exosomal CD82, and serum CA19-9 for pancreatic cancer screening." (PMID 35159011, 2022). "Another study demonstrated that combined detection of exosomal GPC1, exosomal CD82, and serum CA19-9 shows excellent promise as a standard method for pancreatic cancer detection." (PMID 33747908, 2021). "KAI1/CD82 expression is decreased in malignant tumors and is closely related to malignant progression, metastasis, and prognosis, containing breast, colon, lung, ovarian, nasopharyngeal, liver, and pancreatic cancer." (PMID 34306081, 2021).
gastric cancer (15 papers, 2010 to 2024). A primary or metastatic malignant neoplasm involving the stomach. "Consistently, downregulation of CD82 by miR-197 was found to increase gastric cancer cell aggressiveness and enhance EGFR phosphorylation, ERK1/2 phosphorylation and MMP7 expression." (PMID 38389703, 2024). "They suggested an inversely relationship between CD82 expression and the progression of gastric cancer." (PMID 34222025, 2021). "Later in 2007, decreased expression of CD82 in lymph node and liver metastases of gastric cancer compared with the primary tumors was shown by Yu’s lab." (PMID 34222025, 2021). "Their studies indicated CD82 as a metastasis suppressor in gastric cancer and higher expression of CD82 reduced the metastatic potential." (PMID 34222025, 2021). "In summary, the dominant view is that CD9, CD63, CD82 are metastasis suppressors and are negatively correlated with gastric cancer progression and lymph node metastasis." (PMID 34222025, 2021). "Previously it was shown that decreased expressions of CD9 and CD82 were vital for colon cancer metastasis, and particularly reduced expression of CD82 was related with metastatic colon and gastric cancer." (PMID 30289336, 2019). "The reduction of CD9, CD63 and CD82 expression are indicators for the metastatic potential of gastric carcinoma cells." (PMID 21521534, 2011). "The aim of this study was to clarify the clinical significance of TM4SF members CD9, CD63 and CD82 in human gastric carcinoma." (PMID 21521534, 2011). "The metastasis suppression effect of CD82/KAI1 has also been confirmed in gastric cancer." (PMID 34222025, 2021). "Overexpression of miR-362-3p promoted cell metastasis by suppression of CD82 in gastric cancer." (PMID 32432112, 2020). "We also discuss several tetraspanins, including CD81, CD82, TSPAN5, TSPAN9, and TSPAN21 that suppress gastric cancer cell growth." (PMID 34222025, 2021). "Taken together, CD81, CD82, TSPAN5, TSPAN9, and TSPAN21 are regarded as tumor suppressors in gastric cancer to inhibit tumor cell growth and invasion, and enhance the sensitivity to apoptotic stress signals." (PMID 34222025, 2021). "Here, we focus on the insights into the roles and molecular mechanisms of three tetraspanins involved in gastric cancer cell metastasis, CD9, CD63, and CD82 (also known as KAI1)." (PMID 34222025, 2021). "miR-362-3p targeted by CD82 induced tumor formation, affected epithelial-mesenchymal transition (EMT) processes, and promoted the migration and invasion of gastric cancer cells." (PMID 30155491, 2018). "And in the future, we can also establish a gastric cancer cell model overexpressing CD9, CD63 or CD82, by using a plasmid vector." (PMID 21521534, 2011). "In general, the expression of TSPAN8, CD151, TSPAN1, and TSPAN4 is increased in gastric cancer tissues and enhance the proliferation and invasion of gastric cancer cells, while CD81, CD82, TSPAN5, TSPAN9, and TSPAN21 are downregulated and suppress gastric cancer cell growth." (PMID 34222025, 2021). "The classification of gastric cancers according to CD9, CD63 and CD82 expression might be useful in identifying patients for whom intensive adjuvant therapy is warranted." (PMID 21521534, 2011). "However, whether CD82 is a metastasis suppressor gene in gastric cancer was not verified at that time." (PMID 34222025, 2021).
ovarian carcinoma (14 papers, 2013 to 2024). A malignant neoplasm originating from the surface ovarian epithelium. "It has reported that glycosylation of CD82 at N157 is necessary for CD82-mediated inhibition of ovarian cancer cells migration and metastasis." (PMID 38755675, 2024). "The results reported till now clearly demonstrate a pivotal role of CD82 glycosylation at N157 in the inhibition of ovarian cancer cell motility in vitro." (PMID 32483464, 2020). "EpCAM, claudin-4 and −7, and CD82 coexpression correlated with the metastasis and drug resistance in ovarian cancer." (PMID 32091301, 2020). "The expression of CD82 in human biopsies from primary and metastatic ovarian cancers was analyzed using IHC." (PMID 32483464, 2020). "Taken together, ovarian cancer frequently expresses a complex of EpCAM, claudin-4 or −7 and CD82 that is located in TEMs." (PMID 32091301, 2020). "CD82-enriched exosomes significantly impaired ovarian cancer cell migration in contrast to exosomes derived from control and N157Q mutant cells." (PMID 32483464, 2020). "We further uncovered a previously undescribed mechanism that MGAT3 is a critical glycosyltransferase, which promotes CD82 glycosylation in ovarian cancer cells." (PMID 32483464, 2020). "We demonstrated that glycosylation of CD82 at Asn 157 is a fundamental post-translational modification which is required for CD82-mediated inhibition of ovarian cancer metastasis in vitro and in vivo." (PMID 32483464, 2020). "Exosomes enriched in CD82 significantly inhibited ovarian cancer cells adhesion in contrast to control and N157Q enriched exosomes." (PMID 32483464, 2020). "In this study, we demonstrate that glycosylation of CD82 at Asn157 is fundamental to ensure CD82-mediated inhibition of ovarian cancer cell migration and metastasis both in vitro and in vivo." (PMID 32483464, 2020). "We were further interested to get more insight into the molecular mechanism by which CD82 glycosylation at Asn157 inhibits ovarian cancer cells migration." (PMID 32483464, 2020). "Our findings provide compelling evidence for a pivotal role of the glycosylation at N157 in CD82-mediated inhibition of ovarian cancer invasion and metastasis." (PMID 32483464, 2020). "Taken together these data strongly imply that the glycosylation of CD82 at N157 is sufficient for CD82-mediated inhibition of ovarian cancer cells migration." (PMID 32483464, 2020). "Altogether these data demonstrate that CD82 glycosylation at N157 is a determinant post-translational modification responsible for CD82-mediated inhibition of ovarian cancer cell migration in vitro." (PMID 32483464, 2020). "Similarly, EVs bearing the CD82 protein reduced the adhesiveness of recipient ovarian cancer cells depending on CD82 N-glycosylation at Asn157." (PMID 39598633, 2024). "Furthermore, expression pattern of CD82 in lung, pancreatic and ovarian cancer cell lines revealed a molecular weight ranging between 35 and 55 kDa." (PMID 32483464, 2020). "Furthermore, we reveal that the glycosyltransferase MGAT3 is responsible for CD82 glycosylation in ovarian cancer cells." (PMID 32483464, 2020). "Besides ovarian cancer progression, the complex of EpCAM/claudin-7/CD82 involved in the apoptosis resistance." (PMID 32091301, 2020). "In metastasizing and cisplatin-resistant ovarian cancer cells, claudin-4 or-7/EpCAM/CD82 complex has been detected and the question arose whether the interactions were direct or indirect." (PMID 32091301, 2020). "However, the role of CD82 post-translational modification and its impact on ovarian cancer metastasis remain largely uncharacterized." (PMID 32483464, 2020). "Metastatic ovarian cancers express reduced levels of MGAT3 which in turn may result in impaired CD82 glycosylation." (PMID 32483464, 2020). "Since integrin α5β1 contributes to cellular adhesion to fibronectin, we wondered whether the N157 glycosylated CD82 might inhibit the adhesion of ovarian cancer cells by disrupting the integrin-fibronectin interaction." (PMID 32483464, 2020).
ovarian carcinoma (continued). "Interestingly, MGAT3 is significantly downregulated in ovarian cancer metastasis that contributes at least in part to provoke low glycosylation of CD82." (PMID 32483464, 2020). "Knockdown MGAT3 in the ovarian cancer cell lines using shRNA impaired the glycosylation of CD82." (PMID 32483464, 2020). "We next investigated whether the glycosylation of CD82 has any impact on ovarian cancer cells migration." (PMID 32483464, 2020). "Moreover, since the generation of driving forces required for cellular migration results in cellular spreading, we evaluated the impact of CD82 glycosylation on the spreading capacity of ovarian cancer cell lines." (PMID 32483464, 2020). "All these data corroborate that CD82 is highly glycosylated in ovarian cancer cells and indicate that the reduction of 55 kDa CD82 and the concomitant increase in smaller molecular weight fractions in metastatic ovarian cancer can be attributed to impaired CD82 glycosylation." (PMID 32483464, 2020). "Several clinical studies have shown that CD82 is related to metastases and is downregulated in the advanced stages of various epithelial malignancies, including prostate, colon, lung, pancreatic, breast, and ovarian cancers." (PMID 28030805, 2017). "In addition, the palmitoylation of epithelial cell adhesion molecule (EpCAM) affects the formation of a complex among EpCAM, claudin isoforms, and KAI1/CD82, which is important in ovarian cancer progression, whereas 2‐BP treatment inhibits EpCAMP‐CLDN‐KAI1/CD82 complex formation." (PMID 36018061, 2023). "Interestingly, we additionally demonstrated that treatment of ovarian cells with CD82-enriched exosomes efficiently inhibits ovarian cancer cells adhesion and migration in vitro that may represent novel strategies for ovarian cancer metastasis therapies." (PMID 32483464, 2020). "Thus, we also asked, whether chemoresistance of human ovarian cancer was so correlated with EpCAM, claudin-4 and −7, and CD82 coexpression/complex formation." (PMID 32091301, 2020). "In fact, overexpression of CD82 but not N157Q mutant strongly inhibited stress fiber formation in ovarian cancer cells." (PMID 32483464, 2020). "No significant changes of CD82 expression were found at different stages of ovarian cancer." (PMID 32483464, 2020). "However, the role of CD82 in ovarian cancer metastasis has not been investigated." (PMID 32483464, 2020).